THAP11 (THAP domain containing 11)
Description:
Transcription factor, which has both transcriptional activation and repression activities. Also modulates chromatin accessibility. In complex with HCFC1 and ZNF143, regulates the expression of several genes, including AP2S1, ESCO2, OPHN1, RBL1, UBXN8 and ZNF32. May regulate the expression of genes that encode both cytoplasmic and mitochondrial ribosomal proteins (By similarity). Required for normal mitochondrial development and function. Regulates mitochondrial gene expression, including that of components of the electron transport chain (By similarity). Involved in the maintainance of pluripotency in early embryonic cells, possibly through its action on mitochondrial maturation which is required to meet high energy demands of these cells (By similarity). Required for early development of retina, preventing premature exit of retinal progenitor cells from the cell cycle. This effect may also be mediated by its action on mitochondria (By similarity). Through the regulation of MMACHC gene expression, controls cobalamin metabolism. Required for normal brain development and neural precursor differentiation (By similarity). Involved in cell growth.
Synonyms: HRIHFB2206; CTG-B45d; CTG-B43a; RONIN; MAHCL; SCA51
Tractability: PROTAC: ubiquitination databases record sites on it; its protein half-life has been measured.
Gene: Protein-coding gene on chromosome 16 (67,842,320 to 67,844,195, forward strand). Ensembl gene ENSG00000168286.
Subcellular location: Nucleus; Cytoplasm
Subcellular location (Human Protein Atlas): Nucleoplasm; Cytosol
Gene Ontology:
Molecular function: core promoter sequence-specific DNA binding; DNA binding; DNA-binding transcription repressor activity, RNA polymerase II-specific; protein binding; RNA polymerase II cis-regulatory region sequence-specific DNA binding; zinc ion binding; DNA-binding transcription factor activity, RNA polymerase II-specific; DNA-binding transcription activator activity, RNA polymerase II-specific; RNA polymerase II transcription regulatory region sequence-specific DNA binding
Biological process: negative regulation of transcription by RNA polymerase II; regulation of transcription by RNA polymerase II; positive regulation of transcription by RNA polymerase II
Cellular component: cytoplasm; nucleoplasm; nucleus; chromatin
Genetic constraint (gnomAD): Loss-of-function variants: 8 observed, 21.19 expected, observed/expected ratio (o/e) 0.38, 90% interval 0.22 to 0.68. The synonymous counts are far from expectation, so gnomAD's model fits this gene poorly and the ratio says little. Missense variants: 274 observed, 403.38 expected, observed/expected ratio (o/e) 0.68, 90% interval 0.62 to 0.75. Synonymous variants: 221 observed, 179.42 expected, observed/expected ratio (o/e) 1.23, 90% interval 1.1 to 1.38.
Gene-disease validity (ClinGen):
ClinGen rates the evidence that THAP11 causes each of these diseases.
methylmalonic aciduria and homocystinuria (autosomal recessive): Limited. An inborn error of vitamin B12 (cobalamin) metabolism characterized by megaloblastic anemia, lethargy, failure to thrive, developmental delay, intellectual deficit and seizures.
Homologues: Orthologues: chimpanzee THAP11 (98% identical), rabbit THAP11 (97% identical), macaque THAP11 (96% identical), pig THAP11 (95% identical), rat Thap11 (94% identical), mouse Thap11 (92% identical), guinea pig THAP11 (92% identical), tropical clawed frog thap11 (49% identical), zebrafish thap11 (43% identical).
Diseases named in the same sentence as THAP11 in open-access papers:
THAP11 is named in the same sentence as 29 diseases in open-access papers, as found by Europe PMC text mining. Sharing a sentence is not in itself a finding about the gene and the disease. The quoted sentences say what the papers report.
Ataxia (4 papers, 2024 to 2025). Ataxia refers to impaired coordination of voluntary muscle movement. "A CAG repeat expansion in THAP11 was recently found to be associated with spinocerebellar ataxia in two Chinese families." (PMID 39651830, 2025). "This was exemplified in our study, as during the project, two additional ataxia‐associated STR expansions were identified; THAP11 (‘SCA51’) and ZFHX3 (recently identified as the basis of SCA4)." (PMID 40007153, 2025). "A further case with ataxia and Parkinson’s disease was identified through the UK Biobank, but in addition to the THAP11 STR expansion, they were also found to have a CAG STR expansion in CACNA1A, consistent with SCA6." (PMID 38760634, 2024). "In the following section, we will discuss SCA27B, due to a STR expansion in FGF14, and ataxia due to a STR expansion in THAP11, proposed as ‘SCA51’." (PMID 38760634, 2024). "We discuss genetic forms of ataxia related to recently discovered genes or gene variant types, including STR expansions in RFC1 (CANVAS), FGF14 (SCA27B) and THAP11 (‘SCA51’), as well as discussing SCA4, for which the genetic basis has only recently been discovered." (PMID 38760634, 2024).
colon cancer (2 papers, 2014 to 2020). "Interestingly, it is upregulated in lung cancer and ovary cancer and downregulated in liver cancer, kidney cancer, and colon cancer, suggesting the important role of THAP11 in cancer." (PMID 32908912, 2020). "However, in SW620 colon cancer cells, THAP11 knockdown led to a marked decrease in cell proliferation." (PMID 32908912, 2020). "However, immunohistochemical analysis of human colon cancers revealed increased THAP11 expression in both primary tumors and metastases." (PMID 24637716, 2014). "Knockdown of THAP11 in colon cancer cells resulted in a significant decrease in cell proliferation and THAP11 was found to associate physically with the transcriptional coregulator HCF-1 (host cell factor 1) and recruit HCF-1 to target promoters, then mediating transcriptional regulation." (PMID 24637716, 2014).
gastric cancer (2 papers, 2020 to 2022). A primary or metastatic malignant neoplasm involving the stomach. "THAP1 has been associated with DYT6 dystonia, THAP5 and THAP1 have been linked to apoptosis, the LRRC49/THAP10 bidirectional gene pair is involved in breast cancer, and THAP11 has been implicated in colon and gastric cancers." (PMID 35893234, 2022). "THAP11 is differentially expressed during human colon cancer progression and acts as a cell growth suppressor by negatively regulating the c-Myc pathway in gastric cancer." (PMID 35893234, 2022). "We also found cell growth suppression induced by THAP11 was rescued by c-Myc overexpression, further confirming that THAP11 suppresses gastric cancer cell growth via the c-Myc pathway." (PMID 32908912, 2020). "THAP11 acts as a cell growth suppressor and exerts its role possibly through negatively regulating c-Myc pathway in gastric cancer." (PMID 32908912, 2020).
cervical cancer (1 paper, 2018). A primary or metastatic malignant neoplasm involving the cervix. "We speculate that down-regulation of THAP11 could promote invasion and migration of cervical cancer Hela cells." (PMID 29484123, 2018).
hepatic carcinoma (1 paper, 2020). "A study has shown that proliferation of HepG2 hepatic carcinoma cells significantly increased after endogenous THAP11 knockout." (PMID 32908912, 2020).
hyperhomocysteinemia (1 paper, 2022). A serious metabolic condition caused by mutations in the MTHFR gene, medications, or nutritional deficiency. "Combined methylmalonic acidemia (MMA) and hyperhomocysteinemias are inborn errors of vitamin B12 metabolism, and mutations in the transcriptional regulators HCFC1 and RONIN (THAP11) underlie some forms of these disorders." (PMID 35013307, 2022).
Intellectual disability (1 paper, 2025). "However, we identified three people with THAP11 alleles containing ≥45 repeats: two with intellectual disability, of European genetic ancestry (47 repeats), and one control of American genetic ancestry (45 repeats)." (PMID 39651830, 2025).
melanoma (1 paper, 2023). A malignant, usually aggressive tumor composed of atypical, neoplastic melanocytes. "Module M3 contained JUND, SOX2, THAP11, and JUN, as well as regulators for C5 Melanoma MAGEA4, C6 Melanoma GJB2, C2 melanoma EDNRB, and C1 melanoma CDH19." (PMID 37435067, 2023).
nutritional deficiency (1 paper, 2023). "Since the mouse model was obtained through genetic engineering and the other models by a nutritional deficiency of VitB12, it was questioned whether the alteration in “Ribosome” pathway was directly linked to THAP11 mutation." (PMID 36683116, 2023).
teratocarcinoma (1 paper, 2019). A germ cell tumor characterized by the presence of an embryonal carcinoma component and a teratoma component. "Knocking out of the mouse THAP11 gene ‒which is named Ronin ‒was lethal in early embryonic development stages, while overexpression of Ronin in ESCs prevented the cell from differentiation and promoted teratocarcinoma formation." (PMID 34466492, 2019).
cancer (2 papers, 2024). A tumor composed of atypical neoplastic, often pleomorphic cells that invade other tissues. "However, the cases where TF and TPAC scores do have a consistent direction of association for a cancer type across all of the Hallmark gene sets, e.g, KLF13, THAP11 and IRF7 for GBM, are consistent with prior findings on TFs whose activity is linked to cancer (KLF13, THAP11, and IRF7)." (PMID 38206988, 2024).
tumor (2 papers, 2020 to 2021). "AP-1 factors and STAT3 are particularly important for transformation in our model, and loss of ETS, KLF/SP1, THAP11, CREB, ZBTB33, or CEBP inhibits transformation or tumor growth in other cellular or animal models." (PMID 33523865, 2021). "In summary, THAP11 plays an important role as tumor suppressor in the pathogenesis of GC, and it negatively regulates c-Myc oncogene expression possibly through transcriptional repression." (PMID 32908912, 2020). "THAP11 also functions as a tumor-promoting factor in teratocarcinoma of mice." (PMID 32908912, 2020).
autosomal dominant disease (1 paper, 2025). Autosomal dominant form of disease. "Given that SCA51 is an autosomal dominant disease and THAP11 is an important transcription factor, SCA51 offers a unique opportunity to investigate how polyQ expansion induces transcriptional dysregulation and brain region–specific neurodegeneration." (PMID 40459937, 2025).
neurological disease (1 paper, 2025). "We harnessed the UKB to further evaluate the potential association of THAP11 expansions with neurological disorders." (PMID 39651830, 2025).
THAP11 also shares sentences with these, for which no sentence is quoted: Adult onset (1 paper); breast carcinoma (1); cardiomyopathies (1); cblC (1); cerebellar ataxia (1); chronic myeloid leukemia (1); degenerative disease of the nervous system (1); dentatorubral-pallidoluysian atrophy (1); hereditary cerebellar ataxia (1); homocystinuria (1); methylmalonic acidemia (1); neuropathy (1); presbycusis (1); schizophrenia (1); spinocerebellar ataxia type 4 (1).